TMTC1 (transmembrane O-mannosyltransferase targeting cadherins 1)
Description:
Transfers mannosyl residues to the hydroxyl group of serine or threonine residues. The 4 members of the TMTC family are O-mannosyl-transferases dedicated primarily to the cadherin superfamily, each member seems to have a distinct role in decorating the cadherin domains with O-linked mannose glycans at specific regions. Also acts as O-mannosyl-transferase on other proteins such as PDIA3.
Synonyms: ARG99; OLF; FLJ31400; FLJ41625; TMTC1A
Tractability: Antibody: UniProt predicts a signal peptide or a membrane-spanning region.
Gene: Protein-coding gene on chromosome 12 (29,500,840 to 29,784,759, reverse strand). Ensembl gene ENSG00000133687.
Subcellular location: Membrane; Endoplasmic reticulum
Subcellular location (Human Protein Atlas): Cytosol; Nucleoplasm
Gene Ontology:
Molecular function: dolichyl-phosphate-mannose-protein mannosyltransferase activity; mannosyltransferase activity
Biological process: protein O-linked glycosylation via mannose; RNA processing
Cellular component: endoplasmic reticulum; membrane
Genetic constraint (gnomAD): Loss-of-function variants: 60 observed, 92.37 expected, observed/expected ratio (o/e) 0.65, 90% interval 0.53 to 0.81. The upper end of that interval is the gene's LOEUF score, 0.81, which puts it in group 3 of 6, group 1 being the genes least tolerant of losing a copy. Missense variants: 1,005 observed, 1,034.9 expected, observed/expected ratio (o/e) 0.97, 90% interval 0.92 to 1.02. Synonymous variants: 419 observed, 403.2 expected, observed/expected ratio (o/e) 1.04, 90% interval 0.96 to 1.13.
Homologues: Orthologues: chimpanzee TMTC1 (99% identical), macaque TMTC1 (98% identical), pig TMTC1 (93% identical), dog TMTC1 (93% identical), mouse Tmtc1 (88% identical), rat Tmtc1 (88% identical), rabbit TMTC1 (78% identical), guinea pig TMTC1 (76% identical), zebrafish tmtc1 (63% identical), tropical clawed frog tmtc1 (59% identical). Paralogues in human: TMTC2 (29% identical), TMTC4 (29% identical), TMTC3 (27% identical), CFAP70 (12% identical), IFT88 (12% identical), TTC7B (12% identical), TTC7A (11% identical), TTC6 (11% identical), TTC34 (10% identical), BBS4 (9% identical), TTC16 (8% identical), TTC13 (8% identical), and 2 more.
Diseases named in the same sentence as TMTC1 in open-access papers:
TMTC1 is named in the same sentence as 25 diseases in open-access papers, as found by Europe PMC text mining. Sharing a sentence is not in itself a finding about the gene and the disease. The quoted sentences say what the papers report.
heart failure (4 papers, 2011 to 2024). Inability of the heart to pump blood at an adequate rate to meet tissue metabolic requirements. "In a prior meta-analysis, variants in TMTC1 were associated with heart failure (HF) in African ancestry populations." (PMID 34992631, 2021). "The gene TMTC1 (rs159702) has been associated with heart failure in an African ancestry population." (PMID 31852448, 2019). "TMTC1 (Transmembrane O-Mannosyltransferase Targeting Cadherins 1, 615855), as a specific gene signature in our rules for dilated cardiomyopathy identification, is shown to be associated with the risk of heart failure, which is a common symptom for such CHD subtype." (PMID 39202774, 2024).
Abdominal obesity (3 papers, 2011 to 2021). Excessive fat around the stomach and abdomen. "A 2011 study using data from the Northern Manhattan Stroke Study identified an interaction of TMTC1 with abdominal obesity contributing to phenotypic variation in left ventricular mass (LVM)." (PMID 34992631, 2021). "Moreover, the interaction of TMTC1 with abdominal obesity may contribute to phenotypic variation of left ventricular mass (LVM)." (PMID 31852448, 2019). "An interaction of TMTC1 with abdominal obesity may contribute to phenotypic variation of LVM." (PMID 21791083, 2011). "In addition, an interaction of genes, e.g. TMTC1 with abdominal obesity, may contribute to phenotypic variation of LVM." (PMID 21791083, 2011).
breast carcinoma (2 papers, 2021 to 2023). "LAMA2 and TIMP4 were found significantly associated and TMTC1 was found less correlated with breast cancer occurrence." (PMID 37238942, 2023). "LAMA2 and TIMP4 were found significantly associated and TMTC1 gene was found less correlated with breast cancer occurrence." (PMID 37238942, 2023). "LAMA2 and TIMP4 were significantly associated and TMTC1 gene was less correlated with breast cancer occurrence." (PMID 37238942, 2023). "We found that LAMA2 and TIMP4 were significantly associated and TMTC1 gene was less correlated with breast cancer occurrence." (PMID 37238942, 2023). "OncoLnc was used to analyse the effect of expression levels of LAMA2, TIMP4, and TMTC1 on the survival of breast cancer patients." (PMID 37238942, 2023). "Expression level of LAMA2, TIMP4, and TMTC1 was higher in all different stages of TCGA breast cancer samples and significantly expressed among different age groups of patients (younger to older age group)." (PMID 37238942, 2023). "OncoLnc was used to analyze the effect of expression levels of LAMA2, TIMP4, and TMTC1 on the survival of breast cancer patients." (PMID 37238942, 2023). "It has also be shown that during the treatment of gastric cancer, differentially downregulated TMTC1 protein is identified in human gastric carcinoma cells, and TMTC1 is also found to be correlated with breast cancer at the functional level." (PMID 34322159, 2021). "In conclusion, our study identified nine key regulators, of which COL11A1, MMP11 and COL10A1 were up regulated and PCOLCE2, LAMA2, TMTC1, ADAMTS5, TIMP4 and RSPO3 were down regulated in breast cancer samples as compared to control samples." (PMID 37238942, 2023). "The genes namely COL11A1, MMP11 and COL10A1 were found up-regulated and PCOLCE2, LAMA2, TMTC1, and TIMP4 were found down-regulated in breast cancer cell lines also." (PMID 37238942, 2023). "The genes namely COL11A1, MMP11 and COL10A1 were found up regulated and PCOLCE2, LAMA2, TMTC1, ADAMTS5, TIMP4 and RSPO3 were found down regulated in breast cancer." (PMID 37238942, 2023). "Among these key genes COL11A1, MMP11 and COL10A1 were highly expressed and PCOLCE2, LAMA2, TMTC1, ADAMTS5, TIMP4, and RSPO3 were having lower expression levels in breast cancer samples." (PMID 37238942, 2023). "Moreover, we further deeply investigated the role of LAMA2, TMTC1 and TIMP4 genes in breast cancer prognosis." (PMID 37238942, 2023).
gastric cancer (2 papers, 2021 to 2023). A primary or metastatic malignant neoplasm involving the stomach. "TMTC1 has been also found associated with gastric cancer and has been suggested to act as serve as predictive biomarker for gastric cancer treatment." (PMID 37238942, 2023). "Further, we identified 5 prognostic genes (RDH13, CLDN11, TMTC1, UCHL1, and FOXP2) in gastric cancer." (PMID 34322159, 2021). "We revealed that RDH13, CLDN11, TMTC1, UCHL1, and FOXP2 can serve as predictive biomarkers for gastric cancer treatment and the promoter methylation level of these five genes in serum could have prognostic and diagnostic functions in gastric cancer patients." (PMID 34322159, 2021).
schizophrenia (2 papers, 2021 to 2022). A major psychotic disorder characterized by abnormalities in the perception or expression of reality. "Genetic variants of TMTC1 have been linked to brain disorders such as schizophrenia, and their altered glycosylation may contribute to disease development." (PMID 35877430, 2022). "In the results of schizophrenia, known schizophrenia genes like WBP1L (p = 2.24E-14), TMTC1 (p = 3.75E-14), ZNF804A (p = 8.50E-14), TAOK2 (4.82E-12) and so on showed significant association." (PMID 35004692, 2021).
autism (1 paper, 2023). Persistent deficits in social interaction and communication and interaction as well as a markedly restricted repertoire of activity and interest as well as repetitive patterns of behavior. "The Tetratricopeptide repeat (TPR) structural motif present in TMTC1 is also found in other genes such as NAA1566, OGT67–69, TANC270, and TTC2571, all of which are associated with autism and ID." (PMID 37563198, 2023).
cobblestone lissencephaly (1 paper, 2021). "This suggestions is supported by the known mutant phenotype in human TMTC3 (the mutation His67Asp introduces a charge swap and leads to cobblestone lissencephaly; H67 is the position in TMTC3 homologous to H89 in TMTC1)." (PMID 33436046, 2021).
congenital heart disease (1 paper, 2024). A heart disease that is present at birth. "Although shared genes like TMTC1, ART3, and ARHGAP24 are shown to contribute to different congenital heart disease subtypes, they actually play different roles across subtypes." (PMID 39202774, 2024).
cystic fibrosis (1 paper, 2018). Autosomal recessive disorder caused by pathogenic variants in the CFTR gene (cystic fibrosis transmembrane conductance regulator), which encodes a chloride and bicarbonate channel expressed in epithelial cells, and follow the diagnosis criteria. "TMTC1 expression levels distinguished JIA neutrophil activation patterns from those we observed in cystic fibrosis." (PMID 29773851, 2018).
dilated cardiomyopathy (1 paper, 2024). Cardiomyopathy which is characterized by dilation and contractile dysfunction of the left and right ventricles. "In cardiomyocytes, distinct genes such as TMTC1, ART3, ARHGAP24, SHROOM3, and XIST were linked to dilated cardiomyopathy, Neo-Hypoplastic Left Heart Syndrome, hypertrophic cardiomyopathy, HF-Hypoplastic Left Heart Syndrome, and Tetralogy of Fallot, respectively." (PMID 39202774, 2024).
Intellectual disability (1 paper, 2023). "Furthermore, seven intellectual disability candidate genes, TM7SF3, STK38L, ARNTL2, ERGIC2, TMTC1, DENND5B and ETFBKMT have been identified." (PMID 37034680, 2023).
ovarian adenocarcinoma (1 paper, 2023). An adenocarcinoma that arises from the ovary. "We found that TMTC1 expression levels in serous type ovarian adenocarcinomas were significantly higher than those in other tumors." (PMID 37221403, 2023).
ovarian carcinoma (1 paper, 2023). A malignant neoplasm originating from the surface ovarian epithelium. "Here, we showed that TMTC1 protein is overexpressed in ovarian cancer and that high expression levels of TMTC1 are associated with poor prognosis." (PMID 37221403, 2023). "Here, immunohistochemistry showed that TMTC1 was overexpressed in ovarian cancer tissues compared with adjacent normal ovarian tissues, and high TMTC1 expression was associated with poor prognosis in patients with ovarian cancer." (PMID 37221403, 2023). "In this study, we observed that high TMTC1 expression was associated with poor prognosis in patients with ovarian cancer." (PMID 37221403, 2023). "Our findings provide novel mechanistic insights into the role of TMTC1 in ovarian cancer pathogenesis." (PMID 37221403, 2023). "We further used the clinical samples from another tissue microarray (Biomax HOvaC154Su01) to analyze the effect of TMTC1 on the survival of ovarian cancer patients." (PMID 37221403, 2023). "To unravel the underlying mechanism of TMTC1-mediated phenotypic changes in ovarian cancer cells, we identified the protein substrates of TMTC1 using a glycoproteomic approach." (PMID 37221403, 2023). "In this study, we showed that TMTC1 is overexpressed in ovarian cancer and is an independent prognostic factor for the prediction of poor outcomes in patients with ovarian cancer." (PMID 37221403, 2023). "Taken together, integrins β1 and β4 are needed for the TMTC1-mediated migration and invasion of ovarian cancer cells." (PMID 37221403, 2023). "Collectively, these results suggest that TMTC1-mediated invasive behaviors are primarily through integrins β1 and β4 and that TMTC1 is a potential therapeutic target for ovarian cancer." (PMID 37221403, 2023). "Silencing TMTC1 reduced ovarian cancer cell viability, migration, and invasion in vitro, as well as suppressed peritoneal tumor growth and metastasis in vivo." (PMID 37221403, 2023). "We then examined the prognostic value of TMTC1 expression in a public database Kaplan-Meier plotter (KM plotter) based on microarray data from ovarian cancer patients." (PMID 37221403, 2023). "The Kaplan-Meier survival analysis showed that ovarian cancer patients with high TMTC1 expression had poorer survival." (PMID 37221403, 2023). "TMTC1 promotes ovarian cancer cell growth and invasiveness in vitro as well as enhances peritoneal growth and metastasis in vivo." (PMID 37221403, 2023). "Next, we investigated the role of integrin β1 or integrin β4 in the TMTC1-regulated phenotypes of ovarian cancer cells." (PMID 37221403, 2023). "Importantly, silencing of TMTC1 was sufficient to inhibit invasiveness and peritoneal metastasis of ovarian cancer cells." (PMID 37221403, 2023). "TMTC1 promotes the malignant behaviors of ovarian cancer cells in vitro and in vivo." (PMID 37221403, 2023). "Public databases showed that TMTC1 mRNA is highly expressed in ovarian cancer." (PMID 37221403, 2023). "Moreover, TMTC1 promoted migration and invasion of ovarian cancer cells by modifying O-mannosylation and activity of integrins β1 and β4." (PMID 37221403, 2023). "Moreover, the TMTC1-mediated invasiveness of ovarian cancer cells was significantly reversed by siRNAs of integrin β1 or β4." (PMID 37221403, 2023). "Although O-mannosyltransferase TMTC1 is highly expressed by ovarian cancer, its pathophysiological role in ovarian cancer remains unclear." (PMID 37221403, 2023). "Conversely, TMTC1 overexpression promoted these malignant properties in ovarian cancer cells." (PMID 37221403, 2023). "First, we analyzed endogenous levels of TMTC1 in ovarian cancer cells." (PMID 37221403, 2023). "Together with the finding that TMTC1 can regulate cell-laminin adhesion and FAK activity, these results suggest that integrin β1 is involved in the TMTC1-mediated migration and invasion in ovarian cancer cells." (PMID 37221403, 2023).
ovarian carcinoma (continued). "Therefore, the TMTC1-mediated invasiveness of ovarian cancer cells is very unlikely to occur via regulation of calcium levels." (PMID 37221403, 2023). "Interestingly, our data showed that TMTC1 could not significantly affect the O-mannosylation of integrins α3 and α6, the main α subunits in ovarian cancer cells, as revealed by Con A pull-down assay." (PMID 37221403, 2023).
cancer (6 papers, 2021 to 2025). A tumor composed of atypical neoplastic, often pleomorphic cells that invade other tissues. "There was a significant correlation between the expression level of TMTC1 and the infiltration of cancer-associated fibroblasts (CAFs) and endothelial cells." (PMID 39397950, 2024). "We also observed AllChAT at the locus of the MethSig cancer gene TMTC1 after co-amplification with the KRAS oncogene in both tumor PDCs, along with concomitant changes in promoter methylation." (PMID 40931149, 2025). "Initially, to discover the expression pattern of TMTC1 in various cancer tissues, we searched TCGA database and used RNA-seq data from 17 cancer types for comparisons." (PMID 37221403, 2023). "TMTC1 altered the proliferation and survival of cancer cells by participating in cell proliferation and inflammation, as well as the development of endoplasmic reticulum stress." (PMID 36253873, 2022). "In order to investigate the cancer-induced change in TMTC1 expression, as the previous two genes, we extracted the survival data of TMTC1 using TCGA data, and the gene expression data of nine samples in GSE107161 across the three tissue types." (PMID 34322159, 2021). "Promoter hypermethylation will repress the expression of TMTC1 in non-cancer group." (PMID 34322159, 2021).
tumor (5 papers, 2022 to 2025). "We found that the expression level of LAMA2, TIMP4, and TMTC1 was higher in all TCGA tumours and significantly associated with poor survival." (PMID 37238942, 2023). "The silencing of TMTC1 decreased tumor weights and the number of tumor nodules in the peritoneal cavity." (PMID 37221403, 2023). "The results showed that TMTC1 overexpression increased tumor weights and the number of tumor nodules in the peritoneal cavity." (PMID 37221403, 2023). "TSPYL2, JAKMIP1, CIT, and TMTC1 were all significantly downregulated in GBM compared to non-tumor samples (p < 0.001)." (PMID 35877430, 2022). "Expression levels of LAMA2, TIMP4, and TMTC1 across TCGA tumours are shown in." (PMID 37238942, 2023). "We found that the expression level of LAMA2, TIMP4, and TMTC1 was higher in all TCGA tumours." (PMID 37238942, 2023).
neurodevelopmental disorder (2 papers, 2023). A behavioral and cognitive disorder with onset during the developmental period that involves impaired or aberrant development of intellectual, motor, or social functions. "As a result, we identified a dozen candidate genes: TSPAN11 as a potential KS candidate gene, TM7SF3, STK38L, ARNTL2, ERGIC2, TMTC1, DENND5B, and ETFBKMT as candidate genes for the neurodevelopmental disorder, and INTS13, REP15, PPFIBP1, and FAR2 as candidate genes for KS with ID." (PMID 37563198, 2023). "The results identified one potential KS candidate gene (TSPAN11), seven candidate genes for the neurodevelopmental disorder (TM7SF3, STK38L, ARNTL2, ERGIC2, TMTC1, DENND5B, and ETFBKMT), and four candidate genes for KS with ID (INTS13, REP15, PPFIBP1, and FAR2)." (PMID 37034680, 2023).
immune system diseases (1 paper, 2015). "Specifically, eight genes (IRF5, UBA7, TMTC1, GSTM3, FBN2, OAS1, PODXL, ITGA2) were previously associated with immune system diseases in at least one study." (PMID 25874939, 2015).
TMTC1 also shares sentences with these, for which no sentence is quoted: brain disorder (1 paper); cervical cancer (1); epilepsy (1); glaucoma (1); hypertrophic cardiomyopathy (1); hypoplastic left heart syndrome (1); Stroke (1); Tetralogy of Fallot (1).